CCNE2 (cyclin E2)
Diseases named in the same sentence as CCNE2 in open-access papers (continued):
Sharing a sentence is not in itself a finding about the gene and the disease.
lung carcinoma (17 papers, 2008 to 2023). "This suggests that 8PN arrests lung cancer cells generally at G1/S phase, probably through reducing the RB phosphorylation and cyclin E2." (PMID 37013960, 2023). "Our results reveal that 8PN also reduced the levels of phosphorylated RB and cyclin E2 in lung cancer cells, which leads to cell cycle arrest and inhibition of lung cancer cell viability." (PMID 37013960, 2023). "Exosomal miR-30a-5p derived from vascular endothelial cells suppresses the proliferation and migration of lung cancer cells by targeting cyclin E2 (CCNE2)." (PMID 36612314, 2023). "In summary, the high expression of the MCM7 and CCNE2 were significantly related with advanced tumors and worse OS in lung cancer." (PMID 32596300, 2020). "CCNE2 is frequently upregulated in human pulmonary dysplasia and malignancy and is correlated with poor prognosis in lung cancer patients." (PMID 29180617, 2017). "The protein expression of several cyclins including cyclin A2, cyclin B1, cyclin D1, and cyclin E2 was markedly suppressed by GSK-3α knockdown in lung cancer cell lines." (PMID 27049759, 2016). "DMDD has the potential to be an effective agent against lung cancer by inhibiting proliferation, clone formation, migration and causing cell cycle arrest at G1/S through decreasing the expression of DMDD potential targets E2F1 and CCNE2." (PMID 33613291, 2021). "MicroRNA-30d-5p (miR-30d-5p) inhibits lung cancer by targeting cyclin E2 (CCNE2)." (PMID 32615948, 2020). "Thus, the MCM7 and CCNE2 genes can be good indicators for cellular proliferation and prognosis in lung cancer." (PMID 32596300, 2020). "Exosomal miR-144-3p from bone marrow-derived mesenchymal stem cells suppresses the proliferation of lung cancer cells by downregulating cyclin E1 (CCNE1) and CCNE2." (PMID 36612314, 2023). "Among them, four genes involved in the GADD45 signaling pathway (CCNE2, CCND3, CDKN1A, and CCNB1), were reactivated by promoter DNA methylation in the GA-treated lung cancer H1299 cells." (PMID 29416619, 2018). "It has been shown that CCNE2 levels are upregulated in NSCLC tissues, and that miR-30d-5p, by targeting CCNE2, inhibits lung cancer cell proliferation and motility." (PMID 29180617, 2017). "In mice with lung cancer, both of BA and SYK023 obviously decreased the levels of cyclin A2 and cyclin E2, whereas those of p15INK4b and p21CIP1 increased." (PMID 25909174, 2015). "Likewise, baicalein caused cell cycle arrest in G1/S by inhibiting the Akt/mTOR pathway in H1299 and H1650 lung cancer cells, which decreased the expression of the proteins CDK2, CDK4, and cyclin E2." (PMID 37298837, 2023). "In addition to cyclin B members, our results show that cyclin E members, such as CCNE1 and CCNE2, are also targeted by curcumol; CCNE1 plays a role in progression, cell proliferation, and cell cycle arrest of lung cancer cells." (PMID 35520289, 2022). "Thus, CCNE2 and MCM7 can be good indicators for cellular proliferation and prognosis in lung cancer." (PMID 32596300, 2020). "In deed, the expression of cyclin D1, cyclin E2, and cyclin D3 were downregulated in CHRNA5 shRNA transfected lung cancer cells, suggesting that the G0/G1 phase to S phase transition might be regulated by α5-nAChR through cell cyclins." (PMID 28878681, 2017).
non-small cell lung carcinoma (17 papers, 2010 to 2025). A group of at least three distinct histological types of lung cancer, including non-small cell squamous cell carcinoma, adenocarcinoma, and large cell carcinoma. "miR-30d-5p also restrained the proliferation of non-small cell lung cancer cells by downregulating CCNE2, and induced G1/S cell cycle arrest." (PMID 35799836, 2022). "CCNE2 overexpression is observed in a variety of cancers, including non-small cell lung cancer (NSCLC), bladder cancer, leukemia and breast cancer." (PMID 36123627, 2022). "uc.339 is highly expressed in non-small cell lung cancer and acts as a sponge for miR-339-3p, miR-663b-3p, and miR-95-5p, which upregulates cyclin E2, the common target of the three miRNAs, thereby promoting cancer growth." (PMID 34094975, 2021). "A previous study showed that CCNE2 promoted the proliferation, invasion, and migration of non-small cell lung cancer cells." (PMID 28114404, 2017). "CCNE2 shows moderate increases in expression in various malignancies, such as lung, ovarian, nasopharyngeal, colorectal, non small cell lung cancer and leukaemia, and these increases in expression are frequently not correlated to CCNE1 expression." (PMID 20180967, 2010). "Two further studies indicate that CCNE2 is expressed at significant levels in recurrent disease, including therapy-related myeloid leukemia and recurrent non small cell lung carcinoma." (PMID 20180967, 2010). "Downregulation of CCNE1 and CCNE2 can inhibit the development of non-small cell lung cancer cells." (PMID 38994350, 2024). "Similarly, miR-3607-3p acted as a tumor suppressor by sponging CCNE2 to suppresses non-small cell lung cancer." (PMID 31767812, 2019). "Nevertheless, CCNE2 may play an important mechanistic role in non-small cell lung cancer and breast cancer." (PMID 31641220, 2019). "Similarly, miR-144 in BMSC-Exos could down-regulate the expression levels of CCNE1 and CCNE2, thereby regulating the cell proliferation and cell cycle progression in non-small cell lung cancer (NSCLC), and further inhibiting NSCLC progression." (PMID 39161894, 2024). "In Non-small cell lung cancer (NSCLC), it acts as a tumor suppressor, inducing senescence via SMAD3 interaction and repressing cell cycle regulators such as CDK1 and CCNE2." (PMID 41440013, 2025). "In non-small cell lung cancer, the overexpression of miR-3607 in tumor cells could inhibit cell proliferation, migration, invasion and cell cycle by downregulating TGFBR1 and CCNE2." (PMID 32404179, 2020). "The cyclin E2 (CYCE2) is an important regulator in the progression and development of NSCLC, and its ectopic expression promoted the proliferation, invasion, and migration in several tumors, including Non-Small Cell Lung Cancer (NSCLC)." (PMID 29849986, 2018).
glioma (15 papers, 2015 to 2025). A benign or malignant brain and spinal cord tumor that arises from glial cells (astrocytes, oligodendrocytes, ependymal cells). "We have analyzed the level of Reg-2 and its newly identified targets that encode the cyclins CCND1, CCNE1, CCNE2, CCNB1, CCNA2, and the kinases PLK1 and AURKA in glioma tumors." (PMID 38238463, 2024). "For example, KCNQ1OT1, a miR-504 sponge that targets cyclin-dependent kinase 16 in liver cancer and cyclin E2, a miR-370 sponge in glioma act as ceRNA by neutralizing miR-9." (PMID 38875399, 2024). "KCNQ1OT1, an miR-504 sponge that targets CDK16 (cyclin‐dependent kinase 16) in HCC and CCNE2 (cyclin E2), and a miR-370 sponge, in glioma can also act as an ceRNA via neutralizing miR-9." (PMID 32754285, 2020). "In addition, KCNQ1OT1 promoted the aggressiveness of glioma cells through the miR-370/CCNE2 (cyclin E2) signaling pathway." (PMID 34827600, 2021). "The activation of KCNQ1OT1/miR-370/CCNE2 axis resulted in glioma carcinogenesis." (PMID 29970910, 2018). "Importantly, we found that knock-down of FBXW7 increases the levels of several cell cycle proteins, such as E2F1, LSH, KI67, Cyclin A2 and Cyclin E2, both in basic conditions, as well as in miR-10b – depleted glioma cells." (PMID 25738367, 2015). "In case of general glioma, top hub nodes included HER2 and HER4 as part of one cluster; as for astrocytoma, the top hub nodes listed CCNE2 and CDK2 as part of one cluster and VEGF and NRP1 as components of another cluster." (PMID 31952211, 2020). "The results of this study suggest KCNQ1OT1 might contribute to glioma malignancy, and targeting the KCNQ1OT1/miR370/CCNE2 axis may be a promising treatment option for glioma patients." (PMID 34827600, 2021).
prostate carcinoma (12 papers, 2005 to 2024). A carcinoma that arises from epithelial cells of the prostate gland. "Triol caused reduction of Akt1, cyclin E2, cyclin B1, phospho-c-Myc Thr58/Ser62, c-Myc, and phospho-Akt Ser473 in all three prostate cancer cell lines." (PMID 23785446, 2013). "In our MWA screening using 48 antibodies against proteins involved in Akt signaling and cell cycle regulation, we observed that triol caused reduction of Akt1, Akt2, cyclin E2, cyclin B1, phospho-c-Myc Thr58/Ser62, c-Myc, and phospho-Akt Ser473 in all three prostate cancer cell lines." (PMID 23785446, 2013). "In prostate cancer, CCNE2 was proved to be upregulated in patients with prostate cancer and acted as a tumor-promoting protein." (PMID 32487779, 2020). "KEGG pathway enrichment analysis revealed that the significantly enriched pathways were PI3K-Akt signaling, prostate cancer, cell cycle, Wnt signaling, and pathways in cancer; this analysis also showed that CCNE2, MYC, and CREB3L4 were the key involved genes." (PMID 28056099, 2017). "In prostate cancer, CCNE2 is upregulated and considered a tumor-promoting protein." (PMID 38243250, 2024). "Cyclin E2 was shown to induce the G1-S transition in PC3 prostate cancer cells; our results suggest that it may have a similar function in PRAD, given that a lower CCNE2 CN was associated with longer DFS in patients." (PMID 33869043, 2021). "In our present study, the expression of CCNE2 decreased by TW treatment which may increase the sensitivity to hormone treatment of prostate cancer." (PMID 27487134, 2016). "Prostate cancer is an endocrine responsive tumor and may become resistant to endocrine therapy when it becomes metastatic castration-resistant prostate cancer with over expression of CCNE2." (PMID 27487134, 2016). "Cell Senescence caused the differential expression of six genes belonging to the KEGG Pathway Prostate Cancer (PDGFRB, PDGFRA, CCNE2, E2F2, EGFR and ZEB1)." (PMID 35205253, 2022). "These represented cell cycle/mitosis; among others CCNE1, CCNE2, CCNG2, CCNL1, CCNT1, CDK12 and CDKN3, prostate cancer; including the androgen receptor (AR), metabolism as well as targets of the transcription factors E2F, AP2, SP1, ETF and Pax3." (PMID 26698305, 2015). "CCNE2 and BUB1B promotes the proliferation and migration of prostate cancer cells." (PMID 38778150, 2024).
gastric cancer (10 papers, 2008 to 2024). A primary or metastatic malignant neoplasm involving the stomach. "Leukemia and stomach cancer are two cancers with which dysregulated Cyclin E2 expression has been linked." (PMID 38891892, 2024). "A study has demonstrated that CCNE2 may be useful as diagnostic biomarker for early detection of gastric carcinoma for its overexpression in early stages of gastric carcinoma which significantly correlated with differentiation, invasion, and metastasis." (PMID 32596300, 2020). "miR-383 is a tumor suppressor that inhibits cell proliferation, metastasis, and EMT in BC via targeting ETS1, which can also suppress cell cycle progression in gastric carcinoma cells through regulating Cyclin E2 expression." (PMID 36131343, 2022). "Cyclin E2 are also shown to be upregulated at the early stage of gastric cancer." (PMID 33390953, 2020). "Prominent validated targets include CDK6, MYC, CCNE2, MET and GMNN and we furthermore validated the regulation of HDAC1 and SIRT1 also in gastric cancer cells." (PMID 21418558, 2011). "For instance, ectopic transfections of miR-34c were reported to inhibit the growth of gastric cancer cells through suppression of the expression of cyclin-dependent kinase 4 (CDK4) and cyclin E2 (CCNE2) even if no direct interaction was demonstrated between the miRNA and these mRNAs." (PMID 32230926, 2020).
liver cancer (8 papers, 2013 to 2025). An epithelial or non-epithelial malignant neoplasm that arises from the liver. "Cyclin E2 (CCNE2) is a crucial cell cycle protein essential for liver cancer progression." (PMID 40443721, 2025). "Additionally, SIRT3-mediated de-lactylation of CCNE2 inhibits liver cancer cell proliferation, underscoring the regulatory role of lactylation in cell cycle control." (PMID 39868366, 2024). "This study focuses on the effects of CCNE2 lactylation in liver cancer cells, and further research is needed to determine whether CCNE2 lactylation mediates immune suppression by immune cells or cytokines, thereby indirectly promoting liver cancer progression." (PMID 40443721, 2025). "Sirtuin 3 also mediates the delactylation of the cell cycle protein E2 (CCNE2), and the absence of lactylation on CCNE2 suppresses liver cancer growth." (PMID 40535811, 2025). "However, unlike the cyclin E1 proteins, in vitro studies showed that cyclin E2 is not essential for initiating liver cancer." (PMID 38981878, 2024). "Recent research has shown that nonhistone CCNE2 promotes liver cancer cell proliferation, migration, and invasion through lactylation, while NAD‐dependent deacetylase SIRT3 can remove CCNE2 lactylation, thereby regulating the cell cycle and impeding liver cancer progression." (PMID 40443721, 2025).
osteosarcoma (7 papers, 2015 to 2021). A usually aggressive malignant bone-forming mesenchymal neoplasm, predominantly affecting adolescents and young adults. "To summarize, hsa_circ_0000073 enhances osteosarcoma cells’ malignant behavior by sponging miR-1252-5p and modulating CCNE2 and MDM2." (PMID 34568326, 2021). "Results demonstrated that miR-128 knockdown effectively induced osteosarcoma cell apoptosis via decreasing caspase-3 and caspase-9 and arrested Mg63 cells at G2/M phase via inhibition of cyclin D1 and cyclin E2." (PMID 33472642, 2021). "The inhibition of Notch signaling in an osteosarcoma cell line resulted in reduced Cyclin E1, Cyclin E2, and Cyclin D mRNA expression." (PMID 28860516, 2017). "PSMC2 likely drives osteosarcoma via its regulation of cancer-related genes, including ITGA6, FN1, CCND1, CCNE2 and TGFβR210." (PMID 31598166, 2019).
ovarian carcinoma (7 papers, 2011 to 2025). A malignant neoplasm originating from the surface ovarian epithelium. "As a cell cycle progressor, CCNE2 has been shown to promote proliferation of cancer cells, as demonstrated, e.g. in prostate or ovarian cancer." (PMID 41035915, 2025). "Of the 12 upregulated genes VEGFA, HJURP, CCNE2, and RAD51 were also upregulated in the tissue of ovarian cancer patients according to in silico microarray data (Oncomine)." (PMID 31319587, 2019). "A panel of six genes: CCNE2, DKFZp1312, PPIC, EMP2, MAL2 and SLC6A8 may serve as potential markers for CTC derived from breast, endometrial, cervical, and ovarian cancers." (PMID 21827674, 2011). "When we analysed the ploidy of TCGA ovarian cancers, we found, as expected, that CCNE1 occurred at significantly higher levels in whole genome doubled tumours versus non-genome doubled, although CCNE2 did not." (PMID 32823571, 2020).
pancreatic cancer (7 papers, 2013 to 2022). "IC50 of silibinin in AsPC-1 pancreatic cancer cells was determined to be 224.20 and 87.25 μM after 48 and 72 hr, respectively cyclin E2, cyclin A and cyclin B1 were decreased." (PMID 32489562, 2020). "Besides, miR-26a was reported as a suppressor of pancreatic cancer via down-regulating cyclin E2." (PMID 35201478, 2021). "Therefore, we determined whether miR-26a could regulate the pancreatic cancer cell cycle through its target genes, cyclin D2 and cyclin E2." (PMID 24116110, 2013). "By analysing the TCGA database, we found that the expression of PCDH1 was positively correlated with CCND1, CCNE2, VEGFA, MET, CD44 and CD133 expression in pancreatic cancer tissues." (PMID 35864095, 2022). "miR-26a partially influences human pancreatic cancer through the regulation of cyclin E2 and EZH2, but not through cyclin D2." (PMID 24116110, 2013).
bladder cancer (6 papers, 2015 to 2024). "As expected, luciferase reporter assays revealed that MNX1 overexpression activated the luciferase activity of CCNE1 and CCNE2 promoters in the bladder cancer cells, whereas MNX1 downregulation attenuated it." (PMID 30012177, 2018). "Herein, we investigated that MNX1 upregulates CCNE1 and CCNE2 expression to induce proliferation and tumorigenicity in bladder cancer by targeting their promoters." (PMID 30012177, 2018). "Mechanistically, WDR5 regulated various functions in bladder cancer by mediating the transcription of cyclin B1, cyclin E1, cyclin E2, UHMK1, MCL1, BIRC3 and Nanog by histone H3 lysine 4 trimethylation." (PMID 25656485, 2015). "In addition, MNX1 transcriptionally upregulated CCNE1 and CCNE2 by directly bounding to their promoters, which promoted G1–S transition in the bladder cancer cells." (PMID 30012177, 2018). "In summary, our study reveals that the crosstalk between AMPK and Yap1/TEAD4 plays an important role in bladder cancer inhibition by metformin and that it is a critical cell cycle regulator that downregulates CCNE1 and CCNE2 directly." (PMID 31455378, 2019). "In summary, our study reveals that MNX1 upregulation plays an important role in bladder cancer progression and that it is a critical cell cycle promoter that upregulates CCNE1 and CCNE2 directly." (PMID 30012177, 2018). "In bladder cancer, hsa-miR-3687 promotes the growth of bladder cancer cells by downregulating the expression of target gene FOXP subfamily transcription factors and then upregulating the expression of cyclin E2." (PMID 39795889, 2024). "In addition, it has been demonstrated that MNX1 induces bladder cancer proliferation and tumorigenicity by targeting promoters to upregulate CCNE1 and CCNE2 expression." (PMID 36316768, 2022). "Furthermore, we found that MNX1 can accelerate G1–S transition in the bladder cancer cell cycle by transcriptionally upregulating CCNE1 and CCNE2 expression." (PMID 30012177, 2018).
colorectal cancer (6 papers, 2021 to 2025). A primary or metastatic malignant neoplasm that affects the colon or rectum. "The findings provide evidence that HPSE promotes cell proliferation by regulating cell cycle progression via the AKT/p27Kip1/Cyclin E2 axis in BRAF V600E-mutant colorectal cancer." (PMID 36130926, 2022). "Additionally, inhibiting the expression of CCNE2 has been demonstrated to facilitate cell cycle arrest at the G1 phase and thereby decrease colorectal cancer cells in vitro and in vivo." (PMID 39572025, 2024).
neuroblastoma (5 papers, 2015 to 2024). Neuroblastoma (NB) is the most common solid, extracranial childhood tumor. "We evaluated the effect of palbociclib on the Rb/E2F pathway in neuroblastoma cells by measuring the mRNA expression levels of direct E2F target genes, topoisomerase 2A (TOP2A), cyclin E2 (CCNE2), and thymidine kinase (TK1)." (PMID 26225123, 2015).
cervical carcinoma (4 papers, 2015 to 2021). A carcinoma arising from either the exocervical squamous epithelium or the endocervical glandular epithelium. "Others have shown that CHD8 knockdown in cervical carcinoma cells leads to G1 arrest facilitated by downregulation of CCNE2 and TYMS, genes required for transition into S phase." (PMID 26588464, 2015).
Breast Tumors (3 papers, 2011 to 2020). "It is known that CCNE1 and CCNE2 genes are directly or indirectly controlled by c-Myc pathways during mouse development and breast tumors driven by c-Myc." (PMID 27527859, 2016). "Patient’s breast tumour and bone metastasis-derived PDX show amplification of FGFR1, MYC, CCNE2, CCND1 and AURKA." (PMID 32792481, 2020). "The CNA profile of the primary breast tumour, the bone metastasis and the PDX, were highly similar with focal amplification of FGFR1, FGFR2 and CCND1 and CN gains of CCNE2." (PMID 32792481, 2020).